MTOR (mechanistic target of rapamycin kinase)
Diseases named in the same sentence as MTOR in open-access papers (continued):
Sharing a sentence is not in itself a finding about the gene and the disease.
tumor (continued). "The upregulation of circNRIP1 in GC alters glucose metabolism and autophagy via the miR-149-5p/AKT/mTOR axis, promoting tumor metastasis via exosomal communication." (PMID 37365670, 2023). "It was found that RNF7 act an imperative role in tumor proliferation and radiation-resistance through inactivating NF-κB and mTOR pathway or assembling tumor suppressive proteins, including NF1, DEPTOR, procaspase-3, p21, p27, NOXA, and BIM." (PMID 36644576, 2023). "The ASCT2 inhibitor benzylserine can significantly reduce glutamine transport in tumor cells, inhibit the mTOR signaling pathway, and reduce the expression of cell cycle regulators, thus inhibiting cell cycle progression." (PMID 37924140, 2023). "In our research, we discovered a positive correlation between the expression of ZNRF2 and mTOR in various types of tumours." (PMID 37551845, 2023). "On the other hand, the most studied antagonist, i.e., negative regulator of ULK1, is mTOR (mammalian target of rapamycin), a central molecule crucial for the proliferation, growth, and survival of tumor cells." (PMID 36836823, 2023). "Our previous research and other studies have demonstrated that AMPK/mTOR-related autophagy makes a crucial contribution to the treatment resistance of tumor cells 6,35." (PMID 37056929, 2023). "This combination targets the mTOR pathway and disrupts tumor angiogenesis, leading to reduced blood supply to the tumor, inhibited tumor growth, and improved delivery of therapeutic agents to the tumor site." (PMID 37834408, 2023). "In this study, we found that pharmacological VC blocked the activation of the mTOR pathway and tumor growth by degrading Rictor and inducing HMOX1 expression." (PMID 36787291, 2023). "SHR-5 drinking reshaped the tumor metabolism via the inhibition of the mTOR leading to a decreased tumor cell proliferation." (PMID 37370698, 2023). "The localization of mTOR in different cellular compartments of tumor cells seems to be an important factor in tumor progression." (PMID 37176048, 2023). "PTEN is a classical tumor suppressor that negatively regulates AKT/mTOR signaling, and positively regulates autophagy gene expressions." (PMID 38092760, 2023). "While mTOR signaling regulates cell metabolism and proliferation responsible for tumor initiation and progression." (PMID 37735586, 2023). "Another widely reported component of PSORI-CM02 that blocks the mTOR pathway is isorhamnetin, which is known to repress the proliferation of various tumor cells by inhibiting the PI3K/AKT/mTOR pathway." (PMID 37089953, 2023). "Nuclear PD-L1 has been linked to various cellular processes, for example, increasing the anti-apoptotic capacity of tumor cells, promoting mTOR activity, and upregulating glycolytic metabolism." (PMID 37764768, 2023). "HDAC inhibitors have been shown to upregulate expression of the FOXO1 tumor suppressor and they also work synergistically with PI3K/mTOR inhibitors to reduce tumor growth." (PMID 37568705, 2023). "On the contrary, downregulation of mTOR by enhanced glucose consumption results in chemokine secretion, which impairs T cells’ metabolic reprogramming and facilitates tumour immune escape." (PMID 36826068, 2023). "We screened the Z8 small-molecule compound, which targets KK-LC-1 and has excellent tumor cell killing ability by inhibiting MAL2/MUC1-C/PI3K/AKT/mTOR pathway." (PMID 36895039, 2023). "The migration and tube formation of HUVECs treated with CM of BV-treated CRC cells (HCT116 and SW480) with or without inhibitors were examined to further investigate the role of the PI3K/AKT/mTOR signaling pathway in the tumor angiogenesis mediated by BV." (PMID 36732757, 2023). "Loss of LKB1 in mutant KRASG12D tumor cells modulates the expression of PSAT1 and PSPH in an mTOR-dependent manner." (PMID 37187454, 2023).
tumor (continued). "This interaction can potentially influence downstream signaling events that involve Akt/mTOR and NF-κB pathways, which promote tumor cell survival, invasion, and angiogenesis while inhibiting immune cell function." (PMID 38188674, 2023). "By inhibiting the Raf/MEK/ERK pathway, Sorafenib reduces angiogenesis and induces apoptosis in tumor cells, and Sorafenib-acquired resistance is associated with abnormal activation of the PI3K/AKT/mTOR pathway." (PMID 38275586, 2023). "To evaluate the anti-tumor effect of simultaneous inhibition of PI3Kβ/δ and mTOR in vivo, we co-administrated AZD8186 and AZD2014 in an ABC (OCI-Ly10) and a GCB (K422) DLBCL xenograft mouse model." (PMID 36352190, 2023). "In a similar manner, GAS5 sponges miR-106a-5p to finally induce higher levels of p-AKT and p-mTOR in GC cells, which results in a rise of cell proliferation, migration, and invasion, and decline of apoptosis on in vitro models and greater tumor growth in vivo." (PMID 37047267, 2023). "Treatment with PKI-587 and imatinib mesylate effectively inhibited the phosphorylation of Akt and mTOR in PDX tumours, and imatinib inhibited PDGFRB phosphorylation." (PMID 36522480, 2023). "In summary, using clinically relevant PDX HCC models and treatment scenarios, our study showed that the combination of mTOR inhibitors (everolimus and sirolimus) with vinorelbine induces a remarkable tumor response." (PMID 38203186, 2023). "The study on PRPS2 also showed that the expression of hPRPS2 driven by Myc interacted with mTOR, leading to tumor growth." (PMID 37248548, 2023). "Inhibiting mTOR signaling decreases the proliferation of tumor cells or tumor regression, possibly by decreasing epidermal thickness through the downregulation of CK10." (PMID 37887285, 2023). "Abnormal activation of mTOR signaling can lead to multiple adverse outcomes, including tumor formation, neonatal insulin resistance, and adipogenesis." (PMID 37256211, 2023). "Oxidative phosphorylation increases in macrophages in response to let-7a exosomal miR released by the hypoxic tumor cells, leading to the promotion of M2 macrophages and suppression of insulin-Akt-mammalian target of rapamycin (mTOR) signaling pathway and." (PMID 37605155, 2023). "Understanding the complex interplay between the PI3K/AKT/mTOR pathway and the tumor immune microenvironment will undoubtedly provide critical insights for the development of novel immunotherapeutic strategies for UVM treatment." (PMID 37152048, 2023). "The upregulation of mTOR and MYC implicates these classic oncogenic signaling paradigms as mechanisms for growth in a tumor with mtDNA mutations and chromosomal losses." (PMID 37262067, 2023). "This facilitates precise mTOR inhibitor delivery to the brain, amplifying drug concentration at the tumor site." (PMID 37834408, 2023). "Taken together, the small molecule inhibitor PI3K/Akt/mTOR signaling pathway has evolved into an emerging anti-tumor drug." (PMID 37896137, 2023). "Mechanistically, UCHL5 activates the AKT/mTOR signaling pathway and increases c-Myc expression, which promotes tumor occurrence and progression." (PMID 37497216, 2023). "Meanwhile, PI3K/AKT/mTOR signaling inhibition is required for the anti-tumor activity of HER2-targeted treatment, as well as mediating resistance to anti-HER2 therapy." (PMID 37287817, 2023). "PRP1 is known to have cytotastic, antiproliferative, immunomodulatory, and tumor suppressor properties, and is an mTOR inhibitor." (PMID 37046623, 2023). "Preclinical data highlight that mTOR mutations are particularly represented in highly vascularized areas of the tumor since vascularization allows nutrients and growth factors to activate the mTOR pathway." (PMID 37887570, 2023).
tumor (continued). "In our analysis, different aspects of the I-TME and tumors were assessed: TI-ICs, the mTOR pathway, tumor histotype, and grading." (PMID 37190322, 2023). "PI3k/ATK/mTOR signaling pathway was found to be relevant across the metabolism proliferation, invasion, and metastasis of tumor cells." (PMID 36644576, 2023). "The mTOR has been considered to act as a crucial regulator of cell proliferation, tumor growth, and survival in response to molecular growth factors and nutritional status." (PMID 37958310, 2023). "This showed that GPR37 knockdown can inhibit the PI3K/Akt/mTOR signal transduction pathway and tumor occurrence and development." (PMID 37732632, 2023). "Among these KEGG pathways, tumor-related pathways included ubiquitin-mediated proteolysis, insulin signaling pathway, cell cycle, regulation of autophagy, mTOR signaling pathway, ERBB signaling pathway, WNT signaling pathway, and Notch signaling pathway." (PMID 36900050, 2023). "Many studies have confirmed the role of the PI3K/AKT/mTOR signaling pathway in the development of treatment resistance and tumor progression." (PMID 36768370, 2023). "Together, these data demonstrated that prolonged inhibition of mTOR fosters the genomic evolution of tumor cells resulting in the amplification and upregulation of MYC." (PMID 37642941, 2023). "NF1 inactivation leads to the activation of the mTOR pathway and promotes tumour cell growth; therefore, mTOR inhibitors can be used in potential therapies for NF1-deficient patients." (PMID 38024139, 2023). "mTOR inhibitors interrupt the phosphorylation of substrates and block relevant signal transduction, thereby inhibiting the cell cycle, tumor metabolism, and cell survival and exerting antitumor effects through binding with the mTOR binding site." (PMID 38057772, 2023). "The metabolic restriction of T cells caused by tumor glucose consumption leads to decreased mTOR activity, glycolytic capacity, and IFN-γ production in T cells, ultimately facilitating T cell dysfunction and enabling tumor progression." (PMID 37239368, 2023). "Collectively, these results suggest that FMD inhibits the secretion of pro-tumor cell migration cytokine CCL8 by TAMs induced by hypoxia via mTOR-HIF-1α-glycolysis pathway." (PMID 37884960, 2023). "In this study, the combined treatment significantly reduced p-mTOR activation and increased tumor cell apoptosis." (PMID 37160904, 2023). "A common set of proteins including B-Raf, A-Raf, C-Raf, AKT, mTOR, p38-MAPK, and Erk5, which are associated with tumor growth and proliferation were upregulated in osimertinib treated NCI-H1975-OsiR tumors." (PMID 37169941, 2023). "Overexpression of MELK promoted tumor proliferation, migration, stemness, and Akt/mTOR signaling activity." (PMID 37949877, 2023). "The combination of LY2835219 with a mTOR inhibitor significantly suppressed HNSCC tumor growth in vivo." (PMID 36646686, 2023). "Upregulated mTOR signaling promotes tumor growth by enhancing the signaling of growth factor receptors, facilitating migration, angiogenesis, metabolism, and suppressing autophagy." (PMID 37759234, 2023). "Proteomics analyses revealed that the nanoparticles interact mTOR signaling pathway, which is involved in tumor evolution and reoccurrence, and in the development of metastases." (PMID 37660174, 2023). "Several investigators found that Trim44 facilitated tumor development through activation of the AKT/mTOR signaling pathway, including phosphorylated P70S6K in several cases." (PMID 35855640, 2023). "In this section of the study, we validated, at the cellular level through crystal violet staining and CCK8 cell proliferation assays, that OTUD3 has the capacity to inhibit tumor cell growth and proliferation by downregulating the mTOR signaling pathway." (PMID 38288086, 2023). "In summary, saponins play essential roles in anti-tumor activity by regulating the PI3K-Akt-mTOR signal transduction pathway." (PMID 37063281, 2023).
tumor (continued). "The Tie2+ macrophages play a pivotal role in tumor’ neovascularization by activating the PI3K/Akt/mTOR signaling pathway and result in increased expression of angiogenic factor (VEGF, COX-2, MMP-2/-9) in TEMs." (PMID 37304233, 2023). "Previous studies have reported that UBE2C can promote tumor proliferation by activating AKT/mTOR signaling pathway." (PMID 37496990, 2023). "For further experiments, we found that SORT1 is close to mTOR signaling pathway, which lead to the tumor progression." (PMID 36959615, 2023). "Still, the use of palbociclib (a CDK4/6 inhibitor) associated with omipalisib (a PI3K/mTOR dual inhibitor) in ATC in vitro and in vivo models significantly reduced cell proliferation in cell lines and inhibited tumor growth in lower doses." (PMID 38139812, 2023). "ROC curves were drawn to determine the sensitivity and specificity of WNT-1 and mTOR expression in different cellular compartments as indicators of high tumor grade." (PMID 37176048, 2023). "One of the mechanisms of the anti‐tumor effects of statins was explained by the statin‐mediated inhibition of the mammalian target of rapamycin (mTOR) signaling." (PMID 36263515, 2023). "The mTOR protein regulates cell proliferation, apoptosis, and autophagy, and mTOR is consistently stimulated in tumors to maintain tumor cell growth, survival, and proliferation." (PMID 37107564, 2023). "Through cellular function assays, we determined that the PI3K/mTOR inhibitor VS‐5584 exhibited the highest anti‐tumor effect." (PMID 37658623, 2023). "This upregulation promotes autophagy by enhancing lysosomal biogenesis and inhibiting the mTOR pathway, thereby mediating multi‐drug resistance in tumour cells." (PMID 37837401, 2023). "Salmonella induces autophagy and caspase-mediated apoptosis in tumor cells by downregulating the AKT/mTOR pathway, and metabolizes nitrate to nitrite via nitrate reductase and further converts it to nitric oxide in tumors to induce tumor cell apoptosis." (PMID 37765183, 2023). "Through Akt and mTOR, PI3Kγ inhibits the activation of NFκB and stimulates the revitalization of C/EBPβ, activates transcriptional programs which promote tumor development." (PMID 37654704, 2023). "In cancer cells, mTOR can regulate protein translation and participate in the regulation of growth and autophagy in tumor cells." (PMID 38139250, 2023). "A previous in vivo report revealed that miR-221 overexpression promoted tumor growth and invasion through the modulation of the mTOR pathway via DNA damage-inducible transcript 4 (DDIT4)." (PMID 37685331, 2023). "The combination of doxorubicin, metformin, and oxamate resulted in effective and rapid tumor growth inhibition in a xenograft model by inhibiting mTOR phosphorylation and LDH-A gene expression." (PMID 37108109, 2023). "More importantly, the PD-1/PD-L1 pathway can activate the highly active PI3K/AKT/mTOR pathway of tumor cells and promote high intracellular glycolytic metabolism, which results in tumor cell survival." (PMID 37006252, 2023). "Overactivity of mTOR signaling is frequently observed in VHL-deficient ccRCC and related to an aggressive tumor phenotype and poor survival in ccRCC patients." (PMID 36831657, 2023). "mTOR induces metabolic reprogramming in tumours by boosting protein and lipid synthesis and aerobic glycolysis to fuel tumour cells." (PMID 37380971, 2023). "Animal experiments have demonstrated that the RAS/MAPK pathway and AKT/mTOR pathway act synergistically to increase tumor growth." (PMID 36761967, 2023). "One of the main downstream targets of the PI3K/AKT pathway is mTOR, a protein kinase reported to regulate tumour development, metabolism, survival, angiogenesis and immunity." (PMID 36765661, 2023). "Autophagy can be regulated by many signaling pathways, including AKT/mTOR pathways, which are crucial in tumor initiation and progression." (PMID 37239855, 2023).
tumor (continued). "Another in vitro study using the PLC/PRF/5 HCC cell line showed that the Mac-2-binding protein glycan isomer (M2BPGi) activated mTOR and exerted tumor-promoting effects on HCC." (PMID 37631344, 2023). "The enrichment of nuclear mTOR, AR and SMARCD1 in MDA PCa 2b has indicated a more aggressive tumor phenotype in AA PCa vs. EA PCa (i.e., LNCaP, an androgen-dependent EA PCa with much lower nuclear mTOR, AR, and SMARCD1)." (PMID 38023145, 2023). "In conclusion, our results highlight the pathogenetic relevance of eIF4A1 in HCC and recommend further evaluation of the potential usefulness of pharmacological combinations based on eIF4A and mTOR inhibitors in treating this aggressive tumor." (PMID 36768380, 2023). "The elevation of HIF‐2α in hypoxic tumour cells increases the number of CD44+/CD24− MDA‐MB‐231 cells via the modulation of the PI3K/AKT/mTOR axis." (PMID 37156724, 2023). "GCMSCs reduce the frequency of infiltrating NK cells and inhibit their effector function to promote tumor growth through the mTOR signaling pathway." (PMID 37885883, 2023). "All the results suggested that arsenic played a therapeutic role in tumor cells from NSCLC patients through the PI3K/AKT/mTOR-mediated autophagic pathway." (PMID 37371816, 2023). "Since mTOR is a downstream tumor signaling molecule that is associated with signaling pathways such as HER2 and hormone receptor, prohibiting mTOR activation affects upstream signaling that performs an important aspect in tumor cell proliferation." (PMID 37228871, 2023). "Our data support a role for miR-130b in promoting the aggressiveness of LMS, in part by repressing TSC1, a tumor suppressor that controls anabolic cell growth and differentiation through inhibition of mammalian target of rapamycin (mTOR)." (PMID 36701370, 2023). "Expression of the programmed cell death, PD-L1 on tumor cells activates the Akt/mTOR pathway to boost glycolytic metabolism in tumor cells." (PMID 36624636, 2023). "Many classical and critical signaling pathways, such as Wnt/β-catenin, TGF-β and PI3K/Akt/mTOR, are known to be involved in the regulation of tumor growth and progression." (PMID 37691034, 2023). "Studies show that several miRs can reverse the inhibition of tumor growth, progression, and metastasis caused by the PI3K/AKT/mTOR pathway." (PMID 37901797, 2023). "Hyperactivation of TLR-IL1R-mediated Akt-mTOR signaling in SIGIRR-deficient tumors leads to cell cycle progression, loss of heterozygosity of APC, and tumor initiation." (PMID 37869102, 2023). "For IHC analysis, we quantified the expression of p-mTOR and p-S6K using individual specimen, and accordingly confirmed increases in the levels of p-mTOR and p-S6K expression in tumours." (PMID 37076565, 2023). "As an important downstream target of the K-RAS signaling pathway, the role of PI3K-Akt-mTOR axis in tumor occurrence and development has been validated by a variety of researchers." (PMID 36891236, 2023). "A total of 869 downstream genes directly bound by the CXXC5–CRL4B–NuRD complex were identified, including TSC1, which is well recognized for its role in the regulation of mTOR signaling and tumor suppression." (PMID 36539038, 2023). "We found that p-mTOR and p-S6k were highly expressed in tumour samples (FS2 is a representative case)." (PMID 37076565, 2023). "The PI3K/AKT/mTOR signaling pathway was shown to be activated in HCC tumor cells with a pronounced glycolytic metabolism leading to the accumulation of lactate." (PMID 36768977, 2023).